RNU6-665P (RNA, U6 small nuclear 665, pseudogene)
Gene: Small nuclear RNA gene on chromosome 8 (47,667,771 to 47,667,877, forward strand). Ensembl gene ENSG00000207369.
Homologues: Orthologues: chimpanzee U6 (98% identical), macaque U6 (94% identical), guinea pig U6 (89% identical), rat U6 (87% identical), dog U6 (84% identical), pig U6 (84% identical), pig U6 (75% identical), mouse Gm23302 (71% identical). Paralogues in human: RNU6-15P (90% identical), RNU6-166P (90% identical), RNU6-393P (90% identical), RNU6-41P (90% identical), RNU6-1145P (89% identical), RNU6-25P (89% identical), RNU6-35P (89% identical), RNU6-589P (89% identical), RNU6-1 (88% identical), RNU6-1060P (88% identical), RNU6-1152P (88% identical), RNU6-12P (88% identical), and 1290 more.